SOX3 (SRY-box transcription factor 3)
Description:
Transcription factor required during the formation of the hypothalamo-pituitary axis. May function as a switch in neuronal development. Keeps neural cells undifferentiated by counteracting the activity of proneural proteins and suppresses neuronal differentiation. Required also within the pharyngeal epithelia for craniofacial morphogenesis. Controls a genetic switch in male development. Is necessary for initiating male sex determination by directing the development of supporting cell precursors (pre-Sertoli cells) as Sertoli rather than granulosa cells (By similarity).
Synonyms: GHDX; MRGH; PHP; PHPX; SOXB
Tractability: No criterion of Open Targets' tractability assessment is met for any kind of drug.
Gene: Protein-coding gene on chromosome X (140,502,985 to 140,505,069, reverse strand). Ensembl gene ENSG00000134595.
Subcellular location: Nucleus
Subcellular location (Human Protein Atlas): Nucleoplasm
Pathways (Reactome):
Signal Transduction: Deactivation of the beta-catenin transactivating complex
Gene Ontology:
Molecular function: protein binding; sequence-specific double-stranded DNA binding; DNA binding; DNA-binding transcription activator activity, RNA polymerase II-specific; DNA-binding transcription factor activity, RNA polymerase II-specific; RNA polymerase II cis-regulatory region sequence-specific DNA binding
Biological process: sex determination; brain development; central nervous system development; face development; hypothalamus development; negative regulation of neuron differentiation; negative regulation of transcription by RNA polymerase II; neuron differentiation; pituitary gland development; positive regulation of transcription by RNA polymerase II; sensory organ development; regulation of DNA-templated transcription
Cellular component: nucleoplasm; chromatin; nucleus
Homologues: Orthologues: chimpanzee SOX3 (99% identical), macaque SOX3 (99% identical), rat Sox3 (93% identical), mouse Sox3 (93% identical), pig SOX3 (93% identical), rabbit SOX3 (92% identical), dog SOX3 (92% identical), guinea pig SOX3 (91% identical), tropical clawed frog sox3 (52% identical), zebrafish sox3 (51% identical), Drosophila melanogaster Sox21a (28% identical), Drosophila melanogaster Sox14 (21% identical), and 3 more. Paralogues in human: SOX1 (48% identical), SOX2 (43% identical), SOX21 (25% identical), SOX15 (24% identical), SOX14 (23% identical), SOX9 (19% identical), SOX11 (19% identical), SOX7 (19% identical), CFAP65 (19% identical), SOX17 (18% identical), SOX18 (18% identical), SOX6 (18% identical), and 8 more.
Diseases named in the same sentence as SOX3 in open-access papers:
SOX3 is named in the same sentence as 103 diseases in open-access papers, as found by Europe PMC text mining. Sharing a sentence is not in itself a finding about the gene and the disease. The quoted sentences say what the papers report.
hypopituitarism (16 papers, 2015 to 2025). A condition of diminution or cessation of secretion of one or more hormones from the anterior pituitary gland. "Previously, we, and others, have highlighted the importance of SOX3/Sox3 for the hypothalamo-pituitary axis, because mutations in this gene result in a reduction of all pituitary hormones, or hypopituitarism, in both humans and mice." (PMID 39325695, 2024). "Using conditional gene deletion, we show that loss of Sox3 in the central nervous system (CNS) is sufficient to cause hypopituitarism and that this develops postnatally, at the time of weaning." (PMID 39325695, 2024). "In both humans and mice, mutations in SOX3/Sox3, which is located on the X chromosome, are associated with hypopituitarism." (PMID 39325695, 2024). "Additional analysis showed that the duplication also included SOX3, a gene involved in early pituitary organogenesis which is associated with variable degrees of hypopituitarism." (PMID 33184694, 2021). "SOX3 duplications were associated with variable phenotypes, ranging from hypopituitarism, GHD only, intellectual disability (ID), neural tube defect (NTD), Disorders of Sex Development (DSD), or a combination of these phenotypes." (PMID 33184694, 2021). "In our patients with hypopituitarism we found a 6 Mb duplication which includes GPR101, a gene associated with X- linked gigantism, and SOX3, a gene involved in early pituitary organogenesis that is associated with variable degrees of hypopituitarism." (PMID 33184694, 2021). "For hypopituitarism, a duplication of Xq26-27 and SOX3 gene was shown to be causative and dosage sensitive." (PMID 32796691, 2020). "Sox2 appears to be more related to anophthalmia/microphthalmia and hypogonadotropic hypogonadism, while Sox3 tends to be associated to abnormalities of the brain midline and hypopituitarism." (PMID 33324176, 2020). "Significant variability encompassing the SOX3 gene on Xq26, was detected in familial cases presenting X-linked transmission of hypopituitarism." (PMID 32796691, 2020). "Surprisingly in this case, the authors prove that both copy loss and gain of the SOX3 gene result in similar clinical manifestation, including infundibular hypoplasia and hypopituitarism." (PMID 32796691, 2020). "In humans, SOX3 mutations and duplications are associated with X-linked hypopituitarism, a congenital male-specific syndrome that is characterized by pituitary hormone deficiency, infundibular hypoplasia, and incompletely penetrant mental retardation." (PMID 26261758, 2015). "A further indication that the hypopituitarism seen in the Sox3 mutants is likely due to a deficiency of NG2-glia comes from the restoration of both pituitary function and proliferation of NG2-glia with low dose aspirin, while differentiation into mature oligodendrocytes is still impaired." (PMID 39325695, 2024). "SOX3 is associated with hypopituitarism and growth hormone deficiency dwarfism." (PMID 38031145, 2023). "The microcephaly in some patients with SOX3 mutations may be the result of growth hormone deficiency due to hypopituitarism as well as neurogenesis defects." (PMID 38094004, 2023). "SOX3 is critical for the development of the pituitary, brain, and face, and SOX3 mutations may lead to hypopituitarism, intellectual disability, and craniofacial abnormalities." (PMID 35295983, 2022). "However, the duplication also included SOX3, also a single exon gene, which has been associated with variable degrees of hypopituitarism." (PMID 33184694, 2021). "Similarly, SOX3 genetic variants have been reported to result in microcephaly with variable penetrance, in addition to hypopituitarism (ranging from isolated growth hormone deficiency to panhypopituitarism), intellectual disability, neural tube defects, and craniofacial abnormalities." (PMID 38094004, 2023).
hypopituitarism (continued). "There are many causative genes for its isolated form or for multihormonal hypopituitarism, such as TSHβ, TRHR, TBL1X and IRS4 (for heritable isolated central hypothyroidism) and PROP1, HESX1, SOX3 (for multihormonal hypopituitarism)." (PMID 39997750, 2025). "We found that changes in microbiome composition can alter both the NG2-glia phenotype and development of hypopituitarism in Sox3 mutants." (PMID 39325695, 2024). "We also show that external factors such as aspirin or changes in gut microbiota can rescue both the hypopituitarism in Sox3 mutants and renewal of the ME NG2-glia." (PMID 39325695, 2024). "Here, we aimed to characterise the role of SOX3 in the hypothalamus and the etiology of the hypopituitarism." (PMID 39325695, 2024). "We further show that low-dose aspirin treatment, which is known to affect NG2-glia, or changes in gut microbiota, rescue both proliferative defects and hypopituitarism in Sox3 mutants." (PMID 39325695, 2024). "Altogether these data show that the hypopituitarism displayed by Sox3-/Y mice is of hypothalamic origin." (PMID 39325695, 2024). "NG2-glia are the most clearly affected cell type in the Sox3-/Y ME, with both their proliferation and differentiation being disrupted, which suggests that deficits in this population are responsible for the hypopituitarism." (PMID 39325695, 2024). "We and others previously showed that mutations and duplications affecting the transcription factor SOX3/Sox3 result in hypopituitarism, and this is likely of hypothalamic origin." (PMID 39325695, 2024). "In this paper we describe variants in GH1, SOX3 and TGIF1, three genes that are already associated with hypopituitarism." (PMID 34440302, 2021). "Hypopituitarism is the most frequently reported phenotype among males with SOX3, duplication, followed by GHD." (PMID 33184694, 2021). "Patients with mutations in transcription factors (eg PROP1, HESX1, SOX3) require long-term surveillance for evolving ACTH and other pituitary hormone deficiencies." (PMID 26416826, 2015). "Importantly, the appearance of all these defects correlates with development of hypopituitarism suggesting that SOX3 is required postnatally for the functional maturation of the ME." (PMID 39325695, 2024). "Notably this was accompanied by reappearance of the hypopituitarism, with Gh expression being reduced in Sox3-/Y FT animals compared to Sox3+/Y FT animals." (PMID 39325695, 2024). "The reduction in ME cell renewal correlates with the onset of hypopituitarism in Sox3-/Y mutants." (PMID 39325695, 2024). "Therefore, we cannot exclude a tanycytic component of the beneficial effect that low-dose aspirin has on Sox3-/Y hypopituitarism." (PMID 39325695, 2024). "Two previously reported missense variants in SOX3, p.Ser150Tyr and p.Pro142Thr, are located in the N-terminal tail of the HMG (High Mobility Group) domain, and the patients presented with a complex phenotype of syndromic, combined pituitary hormone deficiency." (PMID 34440302, 2021). "Of the reported males with SOX3 duplications, 42% had hypopituitarism, 28% had GHD and 48% had ID." (PMID 33184694, 2021). "The duplication region 11q14.3-q21 encompassing MNTR1B and FAT3 co-occurred with duplication Xq27.3 encompassing the SOX3 gene, which was previously linked to the etiology of ID, hypopituitarism, and speech disorders, but not ASD." (PMID 30647996, 2019). "Therefore, the hypopituitarism displayed by Sox3 mutants is likely to be of hypothalamic origin." (PMID 39325695, 2024). "In conclusion, extra-pituitary findings may provide clues for the diagnosis of particular gene mutations including GLI2, HESX1, LHX4, SOX3, and OTX2 which are involved in the development and differentiation of the pituitary gland resulting in a variety of pituitary hormone deficiencies." (PMID 31782289, 2020).
hypopituitarism (continued). "Moreover, while hypopituitarism seen in both mice and humans lacking SOX3 can be a robust phenotype, we find that it can be modified by external influences, namely by low dose aspirin or gut microbiota." (PMID 39325695, 2024). "Following our relocation and the rederivation by embryo transfer of our animals to the Francis Crick institute (Crick) from the National Institute for Medical Research (NIMR), the hypopituitarism was no longer seen in rederived Sox3-/Y mice, while the cranio-facial defects were still present." (PMID 39325695, 2024). "However, this seems unlikely, as patients with SOX3 duplications have been reported to have hypopituitarism, mental retardation, and XX male sex reversal, which are not features of XLHPT." (PMID 31961795, 2020). "Therefore, SOX3 is necessary for self-renewal, but not differentiation in vitro, in hypothalamic neurospheres and this requirement correlates in time with the onset of hypopituitarism in mutant animals." (PMID 39325695, 2024).
glioblastoma (11 papers, 2018 to 2025). The most malignant astrocytic tumor (WHO grade IV). "SNAI2-null mice are reported to have retarded epithelial migration rates, and SOX3 has been implicated in the malignant behaviour of glioblastoma, EMT, and in the promotion of migration and invasion of osteosarcoma cells." (PMID 31430931, 2019). "This review investigates the role of SOX3 in cancer, as aberrations in SOX3 expression have been implicated in several cancers, including osteosarcoma, breast, esophageal, endometrial, ovarian, gastric, hepatocellular carcinomas, glioblastoma, and leukemia." (PMID 38927713, 2024). "SOX3 is an oncogene in numerous human neoplasms, including osteosarcoma, esophageal carcinoma, glioblastoma, ovarian cancer, and T cell lymphoma." (PMID 41012776, 2025). "In vitro studies in glioblastoma cells have demonstrated that SOX3 is involved in proliferation-related pathways." (PMID 41012776, 2025). "In a series of in vitro studies, the role of SOX3 in glioma and glioblastoma was investigated, revealing its varied impact on cancer cell behavior." (PMID 38927713, 2024). "Further investigations into the functional role of SOX3 through in vitro studies using the U251 glioblastoma cell line demonstrated that downregulating SOX3 positively impacted the wound-healing rate, indicating its influence on cell migration." (PMID 38927713, 2024). "This relationship between CELF2 and SOX3 underscores the intricate regulatory networks influencing glioblastoma cell dynamics." (PMID 38927713, 2024). "Together, these findings paint a complex but enlightening picture of SOX3’s multifaceted role in glioblastoma and glioma, offering valuable insights into its potential as a biomarker and therapeutic target in the fight against these diseases." (PMID 38927713, 2024). "Recently, SOX3 is reported to maintain glioblastoma stem cells in undifferentiated state and further promote the malignant behaviour of glioblastoma cells." (PMID 32363730, 2020). "In glioblastoma cells, the transcription factor SOX3 induces Cripto expression and promotes proliferation, invasion and migration, possibly via the long non-coding RNA SOX2OT, which targets miR-194-5p and miR-122 and results in Cripto expression." (PMID 32517087, 2020). "For example, SOX2OT downregulates the expression of SOX3 by regulating miR-194-5p and miR-122, and SOX3 epigenetically activates SOX2OT expression by binding to the SOX2OT promoter and subsequently forming a positive feedback loop in glioblastoma stem cells." (PMID 32019566, 2020). "For example, SOX2OT can downregulate the expression of SOX3 by regulating miR-194-5p and miR-122, so as to regulate JAK/STAT pathway, inhibit the transcriptional expression of TDGF-1, and affect the biological behavior of glioblastoma stem cells." (PMID 34552054, 2021).
Intellectual disability (11 papers, 2014 to 2026). "SOX3 duplications are implicated in variable phenotypes, including myelomeningocele in both sexes, intellectual disability (of varying severity), and growth hormone deficiency (including panhypopituitarism) in males." (PMID 37221613, 2023). "A more recent paper suggested that the deletion of SOX3 may even be causative of mild intellectual disability." (PMID 30264515, 2018). "In addition, humans with polyalanine tract expansion mutations in SOX3 have a relatively mild phenotype that includes infundibular hypoplasia, hypothamalic-pituitary axis dysfunction and incompletely penetrance of intellectual disability." (PMID 24751947, 2014). "Intellectual disability is present in a subset of individuals with SOX3 mutations, while Sox3 null mice have abnormal corpus callosum development, thereby providing a link between these putative targets and processes with a functional requirement for SOX3." (PMID 24751947, 2014). "Also, SOX3 missense variant was detected in proband with mild intellectual disability." (PMID 33867936, 2021). "The duplication also includes SOX3 (MIM 313430), a gene associated with variable degrees of X-linked hypopituitarism and GHD, sometimes combined with intellectual disability (ID)." (PMID 33184694, 2021). "Both deletions and duplications of SOX3 gene were detected in patients with intellectual disability." (PMID 33867936, 2021). "The two other genes POU3F3 and SOX3 are previously reported to be involved in Central Nervous System Tuberculosis and Mental retardation, respectively." (PMID 29101382, 2017). "In this patient, the phenotypic contribution of the Xq27.1q27.3 duplication involving SRY-BOX3 (SOX3, *313430) could not be further excluded, since duplications encompassing this gene are associated with X-linked hypopituitarism and intellectual disability." (PMID 41595523, 2026). "SOX3 under- and over-expression in males causes multiple pituitary hormone, isolated growth hormone deficiency associated with infundibular hypoplasia, ectopic/undescended posterior pituitary and abnormalities of the corpus callosum with or without intellectual disability." (PMID 33055295, 2020).